EGFR (epidermal growth factor receptor)
Diseases named in the same sentence as EGFR in open-access papers (continued):
Sharing a sentence is not in itself a finding about the gene and the disease.
glioblastoma (continued). "Intriguingly, the commonly used chemotherapeutic cisplatin appears to upregulate EGFR in cisplatin-resistant glioblastoma." (PMID 27153091, 2016). "The amplification and/or overexpression of either EGFR or PDGFR can contribute to the malignant phenotype of distinct subsets of human glioblastoma." (PMID 27344175, 2016). "Constitutive activation of EGFR signaling in glioblastoma occurs also through deletion of exons 2–7 in the EGFR mRNA that leads to expression of the EGFRvIII variant." (PMID 27043632, 2016). "On this basis, we have designed a Phase 1 clinical study of EGFR-targeted, doxorubicin-loaded minicells for effective treatment of human patients with recurrent glioblastoma." (PMID 27050167, 2016). "is a prognostic oncomiR that targets MIG6 and BIM to regulate EGFR and apoptosis in glioblastoma; promotes Th1-cell survival by regulating the proapoptotic gene Bim." (PMID 32309578, 2016). "We have demonstrated this potential for the recurrent duplication of chromosome 7 in glioblastomas, suggesting additional driver genes apart from the known role of EGFR." (PMID 27716417, 2016). "Due to lack of patient material and failed analyses different numbers of glioblastoma tumors are analyzed for EGFR amplification and 1p/19q codeletion." (PMID 26839018, 2016). "Exposure of human carcinoma and glioblastoma cells to radiation in vitro activated Akt, and promoted increased cell survival and proliferation, through activation of EGFR via a ligand-independent mechanism." (PMID 27245053, 2016). "Taken together, these results demonstrate that TAZ can promote proliferation and tumor formation in glioblastoma cells by potentiating the EGFR/AKT/ERK pathway, and provide the evidence for promising target for the treatment of glioblastoma." (PMID 27167112, 2016). "It is noteworthy that in glioblastoma cells cultured as spheroids, the core already constitutes a hypoxic microenvironment which is able to induce EGFR upregulation." (PMID 27717376, 2016). "In fact, in a separate study using glioblastoma as a model, we showed that EGFR-CAR NK cells effectively eradicate glioblastoma (GBM) CSC both in vitro and in vivo." (PMID 27050072, 2016). "Deregulated EGFR signaling has been identified as a critical driver in glioblastoma tumor initiation and progression." (PMID 26906551, 2016). "EGFR is frequently found to be amplified in highly proliferative tumors such as glioblastoma, where it occurs in about 50% of cases." (PMID 27043632, 2016). "Some known oncogenes and tumour suppressors are only captured by RUBIC, such as MDM4 in breast, APC in colon and EGFR in Glioblastoma." (PMID 27396759, 2016). "Berberine-induced inhibition of EGFR has recently been declared in human colon tumor, prostate cancer and human glioblastoma cells." (PMID 27738318, 2016). "Lastly, from all three groups analysed, the tumours developed after injection of p53KD-Ras/EGFR/SrciNPCs closely resembled grade IV glioblastomas." (PMID 26899176, 2016). "In glioblastoma treated with epidermal growth factor receptor inhibitors, drug resistance was mediated via amplification of AKT activity following a compensatory increase in insulin growth factor receptor signaling." (PMID 27826244, 2016). "More recently, berberine downregulate the EGFR-MEK-ERK signaling pathway in human glioblastoma cells." (PMID 27738318, 2016). "In particular, the invasive capabilities of LN428, LN308 and LN229 lines increased by 3.5- to 5-fold upon EGF stimulation, consistent with the strong pro-malignant function of EGFR in glioblastomas." (PMID 26377974, 2015). "The presence of EGFR amplification in histologically pure anaplastic oligodendrogliomas is indicative of glioblastoma." (PMID 25943885, 2015).
glioblastoma (continued). "Elevated expression of urokinase plasminogen activator (uPA) in EGFR-positive glioblastoma cells leads to apoptosis resistance to EGFR tyrosine kinase inhibitors through ERK1/2-dependent repression of Bim expression." (PMID 26405162, 2015). "We demonstrated that HDAC9 promotes tumor formation of glioblastoma via TAZ-mediated EGFR pathway activation, and provide the evidence for promising target for the treatment of glioblastoma." (PMID 25760078, 2015). "The cancer-specific receptor selected in our laboratory is HER2 (human epidermal growth factor receptor 2), a member of the EGFR (epidermal growth factor receptor) family, overexpressed in breast, ovary, gastric carcinomas, glioblastomas, etc." (PMID 25996983, 2015). "PUMA is generally described as mitochondrial, but one group reported interactions between PUMA and the cytosolic domain of the activated EGFR and EGFRvIII proteins, resulting in its cytosolic sequestration in glioblastoma cells." (PMID 26431330, 2015). "Combination with other agents, such as epidermal growth factor receptor (EGFR), can cause regression of glioblastoma by reversing the Warburg effect." (PMID 26398947, 2015). "Although IDH mutation status was not reported in these clustering papers, alterations seen in the non-EGFR amplified group, such as losses on chromosome 13, mirror those seen in our IDHmut glioblastomas." (PMID 26091668, 2015). "In summary, our study demonstrated pre-clinical efficacy of combining TMZ, PLK1 and EGFR inhibitors as treatment for EGFRvIII expressing glioblastomas." (PMID 26059434, 2015). "This strongly suggests that autocrine stabilisation of the PI3K/AKT pathway via EGFR supports starvation resistance of osteosarcoma cells as also observed in glioblastoma cells." (PMID 26526352, 2015). "MiR-7 has been reported to down-regulate EGFR mRNA and other genes in lung breast, and glioblastoma cell cancer cell lines to induce cell cycle arrest and cell death." (PMID 26513016, 2015). "The presence of polysomy of chromosome 7 and amplification of the epidermal growth factor receptor (EGFR) gene is associated with TERT mutations and a prognosis similar to primary glioblastoma in general." (PMID 25943885, 2015). "Aside from promoting cell proliferation, EGFR signaling drives the motility and invasiveness of glioblastoma cells." (PMID 26377974, 2015). "Epidermal growth factor receptor (EGFR) and EGFRvIII analysis is of current interest in glioblastoma – the most common malignant primary CNS tumor, because of new EGFRvIII vaccine trials underway." (PMID 25688333, 2015). "The epidermal growth factor receptor (EGFR) is frequently overexpressed in the most common malignant glioma, glioblastoma (GBM), and represents an important therapeutic target." (PMID 25871395, 2015). "Like cetuximab, nimotuzumab binds to EGFR, and its inhibitory effects were enhanced by reducing abundance of miR-566 in glioblastoma cells." (PMID 26287249, 2015). "For example, miR-21 is highly overexpressed in glioblastoma and has important roles in cellular proliferation, invasion, and apoptosis by regulating the EGFR signaling pathway." (PMID 26134825, 2015). "A permanently activated mutant form of the epidermal growth factor receptor found in glioblastoma promotes self-renewal and tumor progression by inducing autocrine signalling via pigment epithelium-derived factor (PEDF)." (PMID 25992628, 2015). "EGFR is an oncogene that is overexpressed in many cancers including 40–50% of glioblastomas and epithelial cancers." (PMID 25774514, 2015). "Further, our results suggest that Ink4a/Arf(−/−) EGFRvIII glioblastomas that acquired resistance to EGFR inhibition retain oncogenic stress that requiring PLK1 compensation." (PMID 26059434, 2015).
glioblastoma (continued). "Upon treatment with tyrosine kinase inhibitors, glioblastoma cells survive by losing DMs and, thus, downmodulating the expression of EGFR-vIII." (PMID 26075403, 2015). "The EGFR signaling pathway has been a major therapeutic target for various types of cancer, including glioblastoma." (PMID 25909451, 2015). "EGFR activation in glioblastoma promotes cellular proliferation via activation of MAPK and PI3K–Akt pathways, and EGFRvIII is the most common variant, leading to constitutively active EGFR." (PMID 25688333, 2015). "Although here we have put emphasis on feedback circuits, feedforward regulatory loops can also contribute to robust altered activity of EGFR-dependent signaling in glioblastoma." (PMID 25885672, 2015). "Focal homozygous deletion of cyclin-dependent kinase inhibitor 2A (CDKN2A) is a frequent finding in EGFR amplified tumors and these, together with the EGFRvIII, are features of the classical transcriptional subtype of glioblastoma." (PMID 25785247, 2015). "In glioblastomas, inhibition of EGFR has been shown to modulate Rho signaling and reduce cell motility." (PMID 25885672, 2015). "Four glioblastomas with EGFR gene amplification identified by FISH were used in long-range PCR of intron 1 in total RNA as well as DNA." (PMID 25658924, 2015). "Unfortunately, the clinical efficacy of EGFR-specific inhibitors in glioblastoma have fallen below expectations." (PMID 26377974, 2015). "EGFR is an attractive therapeutic target in glioblastoma, with gene amplification noted in 40–60% of patients." (PMID 25785247, 2015). "More recently, it has been shown that in a subset of glioblastomas the EGFR-driven activation of STAT3 requires: a." (PMID 25885672, 2015). "EGFR amplification is observed in 97% of Classical glioblastomas in the TCGA database but infrequently in other subtypes." (PMID 25955030, 2015). "The strong cooperation or synergy between CD151-LB integrins complexes and EGFR in glioblastomas revealed by our study is of high translational significance, as aberrant activation of this RTK occurs in >70% gliomas." (PMID 26377974, 2015). "The key distinguishing feature of these glioblastoma progression routes is the use of different adaptor proteins for aPKC activation: Par6 and p62 for EGFR- and TNFα-directed signaling respectively." (PMID 25885672, 2015). "In particular, the majority of glioblastomas exhibit activated signaling of epidermal growth factor receptor (EGFR), which occurs through gene amplification, activating mutations, and/or receptor overexpression." (PMID 26377974, 2015). "In summary, our study demonstrates that CD151 and its associated α3 integrin are markedly elevated in malignant gliomas, and synergize with EGFR-dependent signaling pathways to drive the aggressive behaviors of glioblastoma cells." (PMID 26377974, 2015). "The response to EGFR inhibition in relapsed glioblastoma (GBM) has been widely studied in recent years but results are non-conclusive." (PMID 24352766, 2014). "Monochloro-GM3 also exhibited a significant inhibitory effect on ΔEGFR, which is a mutant form of EGFR often found in glioblastomas." (PMID 24944646, 2014). "For example, PI3K/Akt activation induced by IGF mediates resistance to EGFR blockade in glioblastoma." (PMID 24709958, 2014). "Here, Wachsberger and colleagues demonstrate that overexpression of a constitutively active form of the epidermal growth factor receptor (EGFR) found in some glioblastomas sensitizes cells to both multimodal cytotoxic therapy and cetuximab." (PMID 25538888, 2014). "As such, consideration should be given to exclude G-CIMP+ glioblastoma patients from EGFR or RTK related therapeutic trials." (PMID 25277177, 2014). "For example, miR-7 is down-regulated in human glioblastoma and directly inhibits EGFR expression by targeting its 3’ UTR." (PMID 24650032, 2014).
glioblastoma (continued). "Several studies have identified epidermal growth factor receptor (EGFR also known as ErbB1/HER1) and its downstream signaling molecules as unregulated in glioblastoma." (PMID 25261371, 2014). "Analysis of TCGA glioblastomas revealed that G-CIMP+ glioblastomas harbored lowered mRNA levels for EGFR and H-Ras." (PMID 25277177, 2014). "The epidermal growth factor receptor (HER1/EGFR) is one of the most frequently dysregulated oncogenes in glioblastoma." (PMID 26056598, 2014). "Owing to the vital role of the EGFR activation in glioblastoma progression, the understanding of its endogenous regulators has been a subject of intense interest." (PMID 25353163, 2014). "Together, our data reveal that drugs targeting PI3K p110α can reduce growth in a subset of glioblastoma tumors characterized by the expression of EGFR/PI3K p110α/p-S6." (PMID 24718026, 2014). "In glioblastoma, one of the most common found abnormalities is the overexpression or aberrant activation of EGFR or its constitutively active mutant EGFRvIII." (PMID 25052069, 2014). "We demonstrate that dopamine antagonists harbor anti-glioblastoma activity that is synergistic when combined with EGFR inhibition." (PMID 24658464, 2014). "Analysis of the TCGA glioblastoma multiforme dataset found that miR-200c expression also shows a statistically significant decrease (p value<1e-5) in samples with high EGFR amplification in this dataset." (PMID 25058589, 2014). "Overexpression of epidermal growth factor receptor (EGFR) family members was reported on glioblastoma (GBM) and medulloblastoma (MB) before." (PMID 24986561, 2014). "A recent report has shown that the cross talk between EGFR and c-Met induces proliferation, invasion and migration in glioblastoma cells and therefore contributes to tumorigenesis." (PMID 24709958, 2014). "In EGFR driven glioblastoma, PKM2 translocates to the nucleus and phosphorylates histone 3 at threonine 11 (H3-T11)." (PMID 25147764, 2014). "There is also ample evidence of an excessive activation of the epidermal growth factor receptor (EGFR) pathway in the majority of glioblastomas." (PMID 25215581, 2014). "These immunoliposomes effectively targeted EGFR-overexpressing glioblastoma cells for the delivery of borocaptate and bioluminescence imaging in vitro and in vivo." (PMID 25190023, 2014). "One of the most common defects in growth factor signalling involves EGFR and amplification occurs almost exclusively in glioblastomas with 40-50% of patients containing EGFR amplification." (PMID 25228849, 2014). "The miR-34a had been shown to target YY1 and the miR-34a-YY1 pathway was demonstrated to regulate expression of epidermal growth factor receptor in glioblastoma multiforme." (PMID 24970812, 2014). "The Epidermal Growth Factor Receptor (EGFR), in particular, is a RTK that is mutated, amplified, or hyperactive in nearly all glioblastomas." (PMID 25277177, 2014). "Rapamycin has also been shown to be effective in clinical trials with EGFR TKIs in the treatment of glioblastoma and renal cell carcinoma." (PMID 24348843, 2014). "In glioblastoma, EGFR-SEPT14 and EGFR-PSPH fusions associated with EGFR amplification were recently observed to result in constitutive activation of EGFR signaling." (PMID 25300797, 2014). "If suppression of EGFR expression is the sole mechanism by which G-CIMP+ glioblastomas down-regulate EGFR signaling, then exogenous expression of EGFR should restore this signaling." (PMID 25277177, 2014). "In this review, the importance of glioblastoma multiforme in signaling pathways initiated by extracellular tyrosine kinase receptors such as EGFR, PDGFR and IGF-1R will be discussed." (PMID 24709958, 2014). "Both full-length LRIG2 and LRIG2 ectodomain promoted the proliferation and inhibited the apoptosis of glioblastoma in vitro and in vivo probably through enhancing the EGFR activation and its downstream PI3K/Akt pathway." (PMID 25353163, 2014).
glioblastoma (continued). "Our results collectively support a key role of EGFR and PDGFRα signaling in survival of Glioblastoma cancer stem cells." (PMID 25380967, 2014). "There are other EGFR mutants present in glioblastoma with different deletions affecting either the extracellular or cytoplasmic domain." (PMID 24709958, 2014). "Subsequent studies suggest that glioblastomas possess dynamic molecular circuits, such that EGFR mediated functions can be substituted by activation of alternate pathways." (PMID 24658464, 2014). "miR-566 activated EGFR signaling and its inhibition sensitized glioblastoma cells to anti-EGFR therapy." (PMID 24650032, 2014). "On the other hand, our current biologic understanding of glioblastoma pathogenesis suggests that EGFR activation occurs later during the evolution of the cancer." (PMID 25277177, 2014). "Using this analytic approach, we found that EGFR signaling is suppressed in G-CIMP+ glioblastomas through epigenetic regulation." (PMID 25277177, 2014). "One of the best characterized glioblastoma proto-oncogenes is the Epidermal Growth Factor Receptor (EGFR)." (PMID 24658464, 2014). "The finding that G-CIMP+ glioblastomas harbor lowered levels of EGFR signaling is largely consistent with the previous observation that IDH mutated, G-CIMP+ glioblastomas exhibited lowered likelihood of PTEN loss of heterozygosity or EGFR amplification." (PMID 25277177, 2014). "It is likely that during glioblastoma pathogenesis, EGFR re-wired the molecular circuitry of the astrocyte as to “hijack” the neurotransmitter-mitogenic signaling axis." (PMID 24657925, 2014). "In this context, many clinical trials have evaluated EGFR tyrosine kinase inhibitors (gefitinib, erlotinib, lapatinib) in recurrent or progressive glioblastomas, or in newly diagnosed gliomas as a monotherapy or in addition to chemotherapy and/or radiotherapy." (PMID 23874590, 2013). "ECOP (EGFR-coamplified and overexpressed protein), a gene which is amplified and overexpressed in at least a third of glioblastomas with EGFR amplification, is known to be a key regulator of NF-κB transcriptional activity that can contribute to cell survival." (PMID 24009623, 2013). "In glioblastoma patient cohort, samples with lower levels of miR-219-5p showed increased levels of total as well as activated phosphorylated form of EGFR." (PMID 23690991, 2013). "Serum spheroid cultures derived from the EGFR amplified glioblastoma xenograft P8 when implanted into the brain of nude rats resulted in highly invasive tumors." (PMID 24349039, 2013). "EGFR is mostly involved in proliferation and is expressed at high levels in many types of cancers, including glioblastoma." (PMID 24330732, 2013). "Since miR-219-5p targeted EGFR and was downregulated in glioblastoma, we looked at the effect of miR-219-5p overexpression on these pathways." (PMID 23690991, 2013). "Glutamate stimulates the up-regulation of epidermal growth factor receptor (EGFR) in glioblastoma cell line, U87." (PMID 23724064, 2013). "In the current study, we have identified that miR-219-5p, one of the downregulated miRNAs in glioblastoma, targeted EGFR by binding to its 3′-UTR." (PMID 23690991, 2013). "In particular, DBA identified genomic breakpoints within epidermal growth factor receptor (EGFR) in two glioblastoma multiforme cell lines, DKMG and CAS-1." (PMID 23637631, 2013). "The increased aberrant activity of the receptor tyrosine kinase (RTK) pathway in glioblastoma is attributed to the deregulation of EGFR in 45% of glioblastoma patients." (PMID 23690991, 2013). "Approximately 20–30% of glioblastoma tumors harbor a constitutively active rearrangement of EGFR, called EGFRvIII, but glioblastoma derived cell lines typically lose EGFR amplification and EGFRvIII expression." (PMID 23637631, 2013).